CD4 (CD4 molecule)
Diseases named in the same sentence as CD4 in open-access papers (continued):
Sharing a sentence is not in itself a finding about the gene and the disease.
AIDS (continued). "The association with AIDS likely represents a higher immunosuppression stage in patients with HIV-HBV co-infection as they had lower CD4 count means, even in the presence of a similar proportion of patients with less than 200 cells/mm3." (PMID 25462190, 2014). "Patients on ART with poor CD4 recovery early in treatment are at greater risk of progression to new AIDS diagnosis or death despite viral suppression." (PMID 24594114, 2014). "In general, the survival probability of an HIV/AIDS patient depends on his/her current state of the disease in such a way that lower CD4 counts are associated with higher risk of transitioning to a worse health state or death state." (PMID 25279328, 2014). "Discovery of the human immunodeficiency virus in 1983–1984 made clear that AIDS is caused by a retroviral ablation of CD4+ T cells, but how and why do AIDS patients get this cancer?" (PMID 25386844, 2014). "The risk of AIDS or death was also reduced for participants with higher CD4 counts at last vaccination (HR 0.8, 95% CI 0.69–0.93 for every 100 cells/uL)." (PMID 25144773, 2014). "It has been documented that most cases of TE in AIDS patients are due to reactivation of latent T. gondii infection, and incidence of the disease is associated with T. gondii IgG seropositivity and low CD4+ T cell count." (PMID 25431660, 2014). "Primary objective of the study was to explore the impact of CD4/CD8<0.8 as independent predictor of HIV-associated non-AIDS (HANA) conditions and multimorbidity (MM) in HIV patients." (PMID 25397456, 2014). "Subjects with baseline CD4+ T cell counts <750 cells/mm3 are at significantly higher risk for progression to AIDS (high-risk progressors, HRPs) than those with CD4+ T cell counts >750 cells/mm3 (low-risk progressors, LRPs)." (PMID 25187947, 2014). "Patients who are initiated on ART and experience rapid CD4 increase, have a lower risk of AIDS illness than those with a slow response." (PMID 24479873, 2014). "ZDVm-experienced and ART-naïve women had similar treatment outcomes (risk of an AIDS event or death, CD4 cell count change) in the first year of therapy." (PMID 24593018, 2014). "In the univariate analysis, a lower CD4/CD8 ratio was associated with increased risk of non-AIDS events (per quartile decrease; OR, 2.0; 95% CI, 1.6–2.5)." (PMID 24497929, 2014). "Human Immunodeficiency Viruses (HIV-1 and HIV-2) cause Acquired Immunodeficiency Syndrome (AIDS), primarily infecting crucial cells of the immune system such as CD4 T-cells, dendritic and macrophages cells." (PMID 24705461, 2014). "Depletion of CD4+ T cells is the most important immune defect and the major contributor to AIDS that these infections cause." (PMID 25505958, 2014). "Further, the third phase or AIDS phase is characterized by a dramatic loss in CD4+T-cells and a strong increase of viral load." (PMID 24963975, 2014). "In adjusted Cox regression models, an absolute CD4 count <200 cells/ml at six months post-ART initiation was associated with greater risk of progression to a new AIDS condition (aHR: 1.6; 95% CI: 1.2–2.2) versus ≥200 cells/ml." (PMID 24594114, 2014). "Anaemia in HIV-infected persons is associated with CD4 cell depletion and progression to AIDS and is one of the strongest predictors of poor responses to antiretroviral therapy (ART) and HIV-related mortality." (PMID 25228991, 2014). "Older age, clinical WHO stage 3 and 4, low CD4 count, and AIDS-defining infectious diagnoses were associated with hospital fatality." (PMID 24713375, 2014). "The CD4/CD8 ratio was also significantly lower in subjects with non-AIDS associated mortality (N = 29) [0.33 (IQR 0.22–0.46), P<0.0001]." (PMID 24497929, 2014). "In the setting of untreated HIV infection, the CD4/CD8 ratio predicts time to AIDS and is associated with pre-ART CD4 and CD8 counts." (PMID 24831517, 2014).
AIDS (continued). "Since CD4+ T cell depletion is a highly diagnostic clinical feature of AIDS, these studies raise an exciting possibility of reversing CD4+ T cell depletion by blocking the inflammasome response with caspase-1 inhibitors." (PMID 24817865, 2014). "The subjects had different risk of progression toward AIDS based on CD4+ T cell count at baseline 10–11 weeks post infection (wpi)." (PMID 25187947, 2014). "Being >10 years old and having higher 12-month risk of AIDS (calculated using the absolute CD4 lymphocyte count and the age) were associated with an increased risk of mortality." (PMID 24688879, 2014). "The association between this ratio and the risk of serious non-AIDS events is robust and maintained within subjects with low CD4 nadir or those with higher CD4+ T-cell count." (PMID 24497929, 2014). "In summary, our data demonstrate an increased frequency of hyponatremia (approximately 53.2%) in Chinese hospitalized HIV/AIDS patients, and that serum sodium concentrations are associated with the CD4+ cell count and clinical stage of HIV/AIDS patients." (PMID 25360785, 2014). "In this review, we explore the evidence in ART-experienced populations on clinical outcomes (i.e. mortality, CD4 and viral load (VL) changes over time, resistance mutations, death and AIDS)." (PMID 24998532, 2014). "Risk of serious non-AIDS events associated with a low CD4/CD8 ratio (categorized by quartiles and by the cut-off of 0.4)." (PMID 24497929, 2014). "Estimated hazard ratios (HRs) were adjusted for transmission risk group, sex, age, year of ART initiation, baseline CD4 count, viral load, and AIDS status, before and after the first year of ART." (PMID 24771333, 2014). "The study results indicated an association between low CD4+ counts at AIDS diagnosis and lower survival, which corroborates the findings of several other studies." (PMID 25398533, 2014). "Acute phase of AIDS is characterized by a net decrease of CD4+ T cells, and the hallmark of the chronic phase is a gradual decrease of the peripheral CD4+ T cells." (PMID 24744753, 2014). "AIDS-defining events on cART occurred at a median time of 6 months, were predicted by low CD4 cell counts, prior AIDS and low BMI at initiation of therapy and were associated with an increased risk of subsequent attrition from the programme." (PMID 25340766, 2014). "Although defined by virologic criteria, HIC status is typically associated with improved clinical outcomes comparable to individuals on VL-suppressive HAART, including higher CD4 counts and reduced risk of developing AIDS and death." (PMID 25144773, 2014). "The independent association between HBV vaccine responses and AIDS or death was even observed in the subset participants with CD4 count >500 cells/uL at last vaccination." (PMID 25144773, 2014). "Intraveneous drug users, age >50 years, HIV RNA >10,000 copies, CD4 <500/mm3, AIDS stage, hepatitis C co-infection and cardiovascular risk factors (diabetes, high blood pressure, and tobacco use) were associated with SME." (PMID 25076050, 2014). "Failure to restore a normal CD4:CD8 T-cell ratio has been linked with an increased risk of non-AIDS related events, such as cardiovascular disease." (PMID 24710051, 2014). "The association of CD4 count recovery with mortality showed a similar trend to that demonstrated between CD4 count recovery and progression to new AIDS diagnosis." (PMID 24594114, 2014). "The risk of TB reactivation during HIV is associated not only to quantitative defects of CD4+ T-cell counts, since many patients develop TB and AIDS well before CD4+ T-cell counts decrease below 350-200/μl." (PMID 24804000, 2014). "This is in line with the results of a large collaborative European study that showed a persistent role of prior AIDS on the risk of death, even in patients with CD4 cell counts ≥500/mm3." (PMID 24727746, 2014). "Age (p=0.002) and baseline CD4 count (p<0.001) were significantly associated with the development of AIDS." (PMID 25095830, 2014).
AIDS (continued). "Classically, FIV and HIV infect CD4+ T cells, causing their depletion and an acquired immunodeficiency syndrome (AIDS), whereas individuals infected by EIAV and SRLV (which do not infect T-cells) have been considered for years non-immunodeficient." (PMID 23917352, 2013). "Evidence from several studies showed that for a given CD4+ T-cell count or viral load, older patients had a greater risk for progressing to AIDS than younger ones." (PMID 24376638, 2013). "We used a definition of late-stage HIV disease of CD4<100 cells/mm3, which portends a major risk for cryptococcal meningitis, a leading cause of AIDS-related deaths in sub-Saharan Africa." (PMID 23383147, 2013). "Immunological suppression and disturbance caused by HIV infection is responsible for the decline in CD4 cell counts and is predictive of both morbidity and mortality from AIDS." (PMID 23573191, 2013). "HIV/AIDS is characterized by severe immune dysfunction associated with marked reduction in CD4+ T cell counts and high plasma HIV-1 viral load." (PMID 24109479, 2013). "It has been well known that development of AIDS following infection with the human immunodeficiency virus (HIV) is associated with impaired cell-mediated immune response due to a reduction in CD4-positive T lymphocytes." (PMID 24058271, 2013). "Older age, a history of AIDS and current CD4 cell count were associated with an increased incidence of ICU admission and receipt of cART was found to be highly protective." (PMID 23331544, 2013). "From the early days on, it was appreciated that the main feature of AIDS is a steady decline of CD4+ T-cells circulating in peripheral blood, causing a significant change in the CD4+/CD8+ T-cell ratio (see:)." (PMID 23985078, 2013). "Lower nadir CD4 counts, higher viral loads and the history of an AIDS-defining illness are associated with poorer neurodevelopmental outcomes, further supporting the need for early ART initiation in children." (PMID 23782482, 2013). "Observational studies suggest that ART initiation at CD4 T cell count >350 cells/μL is associated with lower risk of SNAEs, AIDS-defining illness or death when compared to deferring ART." (PMID 24330529, 2013). "With regard to CD4+ T-cell count within 6 months at diagnosis, AIDS patients with more number of CD4+ T-cells within 6 months at diagnosis had lower risk of death (HR = 0.29 for 50- vs <50, 95% CI, 0.15–0.59, P = 0.001)." (PMID 24376638, 2013). "The 3-year cumulative risk of clinical failure (defined as death, a new AIDS-defining event, or a CD4 count of less than 50 cells/mm3) was 8% in the VL arm and 7.4% in the CD4 arm." (PMID 23940461, 2013). "Traditional markers of HIV disease progression and severity including high plasma viral load, lower CD4 cell counts and/or CD4%, and history of an AIDS defining illness have been associated with poorer neurocognitive performance." (PMID 23782482, 2013). "The consistent activation of CD4 and CD8 T-cells is associated with depletion of CD4 T-cells and increased risk of disease progression to AIDS." (PMID 24348678, 2013). "Nef is a critical factor that enhances virus replication in vitro in primary CD4+ T cells and is clearly associated with AIDS." (PMID 23658518, 2013). "In our bivariate analyses, both untreated AIDS and lower CD4 count were significantly and positively associated with bacteremia." (PMID 24386229, 2013). "Specifically, IFN-γ-producing CD4+ Th1 cells have been shown to be critical for protection in the murine TB model and depletion of CD4+ T cells in AIDS patients renders them susceptible to TB." (PMID 23805289, 2013). "Patients with more CD4+ T-cell count within 6 months at diagnosis was associated with less likelihood to die of AIDS or AIDS-defining illnesses (OR = 0.30 for 50- vs <50, 95% CI, 0.11–0.80, P = 0.017; OR = 0.07 for ≥200 vs <50, 95% CI, 0.01–0.68, P = 0.022)." (PMID 24376638, 2013).
AIDS (continued). "Such individuals were at increased risk of AIDS/death (HR = 2.0, 1.0–3.8) compared to those with a CD4<350 alone." (PMID 24244330, 2013). "The risk of AIDS/death was significantly higher for individuals with severe symptoms, those with ≥1 CD4<350 cells/mm3 or ≥2 CD4 <500 cells/mm3 in the first 6 months [aHR (95% confidence interval) 2.1 (1.4,3.2), 2.0 (1.5,2.7), and 2.3, (1.5–3.5) respectively]." (PMID 24244330, 2013). "In these studies, individuals infected with subtype D had significantly higher rates of CD4+ T-cell loss and a shorter progression time to AIDS or death than other subtypes and recombinants." (PMID 23951241, 2013). "Lower CD4 cell counts and AIDS diagnosis at baseline significantly increased the hazard of AIDS-related and non-AIDS-related causes of death, although the magnitude of the effect of both factors was much higher for AIDS-related causes of death." (PMID 23577074, 2013). "We found that excess mortality risk exist in AIDS patients with more severe disease (lower CD4+ T-cell count at AIDS diagnosis)." (PMID 24376638, 2013). "In the adjusted analysis, we found that older age, lower education, and lower CD4 cell counts significantly increased the hazard of death from non-AIDS related causes." (PMID 23577074, 2013). "We used data from the International Epidemiologic Databases to Evaluate AIDS–Southern Africa (IeDEA-SA) collaboration to estimate mortality for up to 3 y of follow-up associated with starting ART at a range of different CD4 values in children aged 2–5 y." (PMID 24260029, 2013). "Further examination of associated patient data found that while male AIDS patients had significantly higher CD4+ T lymphocyte counts at the time of admission, they had an increased risk of death during hospitalization." (PMID 23741297, 2013). "Patients who start ART at high CD4 counts (≤500 cells/μL) have decreased risk of progression to AIDS and/or death and increased likelihood of immune recovery." (PMID 24376569, 2013). "Our study showed that there was a high prevalence of diabetes among adults with newly diagnosed HIV/AIDS, and that lower CD4 count was associated with an increased risk of diabetes, since the prevalence of diabetes increased with decreasing CD4 count." (PMID 23394285, 2013). "Data from randomized controlled trials suggest that deferral of ART initiation until CD4 T cell count <250 cells/μL was associated with increased SNAEs, AIDS-related events and mortality." (PMID 24330529, 2013). "The key role of chronic immune activation in HIV and SIV pathogenesis is now commonly accepted, as it is so clearly associated with CD4+ T-cell decline and progression to AIDS." (PMID 24133492, 2013). "High plasma viral RNA copy numbers are closely linked with low CD4+T cell counts and are used as an indicator of the disease progression to AIDS." (PMID 23936398, 2013). "AIDS patients have severe defects in CD4+ T cells and are highly susceptible to development of active TB." (PMID 23638187, 2013). "Our study population of treated participants with moderate/high CD4 counts and at low risk for AIDS is also a strength, in that they accurately represent contemporary patients in regions with access to cART." (PMID 23457535, 2013). "In our investigation, non-AIDS-defining causes of death equaled AIDS-defining causes of death despite much lower CD4+ T cell counts among those who died." (PMID 24260125, 2013). "AIDS and immunodeficiency (CD4 cell counts <200 cells/mm3) were associated with an increased risk of ICU admission, while receipt of cART was associated with a reduced incidence of ICU admission." (PMID 23331544, 2013). "In the final model, major depressive disorder was associated with AIDS-related stigma [(OR = 1.65, CI 1.20–2.26)], CD4+ counts of ≥200 [OR 0.43, (CI 0.20–0.91)] and a younger age [OR0.95, CI 0.92–0.98)]." (PMID 23209556, 2012).
AIDS (continued). "Even though some genotypes of E. bieneusi can cause chronic diarrhea and wasting syndrome in AIDS patients once the CD4+ T-lymphocyte count drops below 100 cells/mm3." (PMID 23091702, 2012). "Depression, stressful life events and trauma are associated with a decrease in CD4 T-lymphocytes, an increase in viral load, faster clinical decline, and higher AIDS-related and all-cause mortality." (PMID 22479319, 2012). "The researchers then used stratified multivariate Cox models (a type of statistical analysis method) to estimate the association between CD4 cell counts and the occurrence of a new AIDS-defining event or death." (PMID 22448150, 2012). "SIV causes CD4 depletion in some simian species, but the progression to AIDS is disproportionately faster than in HIV-1 infection of humans." (PMID 22363634, 2012). "For example, malaria is reported to facilitate HIV replication through increased cytokine production and immune cell activation leading to CD4 cell loss and the consequent diagnosis of AIDS-defining conditions." (PMID 22412867, 2012). "Coreceptor switching from early CCR5 usage to late CXCR4 usage in HIV infections is associated with rapid CD4 decline and AIDS development." (PMID 23202514, 2012). "In the absence of any universally effective therapy for cryptosporidiosis, HIV/AIDS patients have shown marked improvement in their cryptosporidium-associated symptoms when antiretroviral therapy has been used to raise their CD4+ count." (PMID 22685452, 2012). "These non-AIDS conditions in HIV patients are associated with CD4+ T cell counts: lower counts are associated with higher rates of liver, cardiovascular, renal, and neurocognitive disorders." (PMID 23908849, 2012). "There is some evidence that prolonged immunosuppression—as assessed by CD4 nadir—is independently linked to increased incidence of non-AIDS-defining malignancies." (PMID 22666562, 2012). "Multivariable analysis showing associations between major depression, AIDS related stigma and CD4 counts." (PMID 23209556, 2012). "We used stratified multivariate Cox models to estimate the association between time updated CD4 cell count and a new AIDS event or death or death alone." (PMID 22448150, 2012). "Despite the slower rate of CD4 cell loss, the probability of being diagnosed with clinical AIDS was higher in all Africans, particularly in SSA cohorts." (PMID 22412867, 2012). "HIV-1, the causative agent of the Acquired Immunodeficiency Syndrome, AIDS, infects target cells that present the entry receptors and co-receptors CD4 and CXCR4/CCR5 on their surface." (PMID 23227982, 2012). "Immunodeficiency, especially that associated with HIV/AIDS, low CD4+ T cells count (≤50 cells per microliter blood), and younger age are all considered risk factor for intestinal microsporidiosis due to E. bieneusi." (PMID 23091702, 2012). "The subsequent emergence of HIV variants that use the CXCR4 coreceptor in roughly half of all infections is associated with an accelerated decline of CD4+ T-cells and rate of progression to AIDS." (PMID 23133358, 2012). "Although TB IRIS and drug interaction are avoided, and MTB is eliminated, the continued high viral load and low CD4 over 6 months pose significant risk of AIDS death." (PMID 23209581, 2012). "This HIV coreceptor switch is clinically significant because it is associated with accelerated deterioration of the CD4+ T-cell population and rate of progression to AIDS." (PMID 23133358, 2012). "The activating allele, KIR3DS1, when present in combination with Bw4, is associated with lower viral load, slower decline of CD4+ T cells and delayed progression to AIDS." (PMID 22571741, 2012). "The human immunodeficiency virus (HIV), the causative agent of AIDS, binds to the CD4 molecules which causes depletion of CD4+ T cells in AIDS patients." (PMID 25408871, 2012). "The hallmark of HIV-1 infection is depletion of CD4 T cells, whose loss leads to the opportunistic infections and cancers characteristic of AIDS." (PMID 22241988, 2012).